G6PD (glucose-6-phosphate dehydrogenase)
Diseases named in the same sentence as G6PD in open-access papers (continued):
Sharing a sentence is not in itself a finding about the gene and the disease.
anemia (continued). "When the patients with dual antiplatelets were excluded, the G6PD‐deficient group using aspirin alone also demonstrated high risks in hemoglobin decline, anemia, and bilirubin increase." (PMID 34369077, 2021). "If known, the cause(s) of anemia should be treated first, and G6PD testing repeated after several weeks." (PMID 34353361, 2021). "Infants with this novel variant showed decreased activity of G6PD, severe anemia, and pathological jaundice, consistent with Class I G6PD deleterious variants." (PMID 32680472, 2020). "Updated information was generated on the prevalence of anaemia and the different G6PD and CYP2D6 variants in the target population." (PMID 31234865, 2019). "G6PD encodes glucose-6-phosphate dehydrogenase, an enzyme that is critical for red blood cell metabolism, as deficiency is known to result in haemolysis, anaemia, hyperbilirubinemia and jaundice." (PMID 30239796, 2019). "Among the million persons who have received primaquine in radical curative doses during mass drug administrations, only 16 persons (mostly likely G6PD deficient) were reported as having experienced severe haemolysis or anaemia." (PMID 29499733, 2018). "In 844 MB-treated African children, two patients developed severe anaemia (Hb < 5 g/dL) during the first days of treatment and both were G6PD deficient." (PMID 29690878, 2018). "Nevertheless, with the 0.75 mg/kg single dose in G6PD deficient people there is an average 1.45 g/dl greater fall in haemoglobin by day 7 compared to placebo, and risks of anaemia (20% drop in haemoglobin) are increased 11-fold." (PMID 28830424, 2017). "The technique is influenced by the concentration of haemoglobin in the blood sample and can result in an estimated value of G6PD activity that is falsely high in subjects with anaemia or iron deficiency." (PMID 28852037, 2017). "The odds ratio of methemoglobinemia was two times higher in children with hemoglobinopathies (sickle cell anemia or glucose-6-phosphate dehydrogenase deficiency (G6PD)) (aOR 1.97, 95 % CI: 1.17, 3.32), or in severe anemia (aOR 1.99, 95 % CI: 1.51, 2.61)." (PMID 27814710, 2016). "We observed possibly important differences in G6PD expression among heterozygous variants, and revealed anemia as the basis of G6PD measurements skewed far above normal." (PMID 25746733, 2015). "Our analysis also revealed a strong association of homo-/hemizygous G6PD genotype with post-dose incidence of anemia (hemoglobin <8 g/dL) 7 days after IPTi treatment." (PMID 26599634, 2015). "A 8 month-old infant presented with acute onset of severe jaundice, anemia requiring transfusion and Glucose-6-Phosphate Dehydrogenase deficiency." (PMID 25048415, 2014). "This decrease in erythrocyte G6PD activity causes hemolysis, and likely plays a role in the pathogenesis of anemia in patients with ESRD." (PMID 25261071, 2014). "Conversely, the association between G6PD rs1050828 with anaemia in females (OR = 4.77, 95%CI 1.80-14.21, p = 0.003) was only observed in the Bantu ethnic group." (PMID 24934404, 2014). "Unlike G6PD Mediterranean, a more severe deficiency in which haemolysis continues until well after the administration of drug is stopped, the haemolytic anaemia caused by G6PD A- is self-limited because only the older red blood cells are destroyed." (PMID 22546009, 2012). "Over 400 million people worldwide suffer from a deficiency of G6PD that results in mild to severe anaemia." (PMID 23006493, 2012). "Only 17 out of 1069 children who were typed were G6PD A- deficient, of these 2/9 treated with CD and 1/8 treated with AL developed severe anaemia." (PMID 21666744, 2011). "Anaemia could also be caused by other factors, such as poor nutrition, as 28 (46.7%) of the anaemic children were non-G6PD deficient." (PMID 41200155, 2025).
anemia (continued). "Further reported conditions that may complicate the introduction of complementary feeding include anemia (iron and folate deficiency; 191, 18.2%), malnutrition (136, 12.9%), and glucose-6-phosphate dehydrogenase (G6PD) deficiency anemia (129, 12.3%)." (PMID 38414687, 2024). "Also, primaquine causes hemolysis anemia in glucose-6- phosphate dehydrogenase (G6PD) deficient patients." (PMID 37093000, 2023). "In G6PD-deficient individuals given 0.25 mg/kg primaquine, severe anaemia was uncommon (between 1/100 and 1/1000) for individuals with baseline haemoglobin concentration ≥ 11 g/dL but common (1/10 to 1/100) for baseline haemoglobin concentrations between 9 and 10 g/dL." (PMID 36109733, 2022). "G6PD and haemoglobinopathies had the strongest associations with anaemia in this population." (PMID 32153098, 2022). "Although our study found an increased risk of anaemia in 194 G6PD-deficient individuals who received SD primaquine, haemoglobin dropped below 7g/dL (Hb0 − Hb7: 8.2–6.8, 8.8–6.0 g/dL) in only two patients, and serious adverse haematological events were few and transitory." (PMID 36109733, 2022). "Likewise, the prevalence of anaemia at the enrolment was 55.0% (11/20), 53.4% (62/116), and 57.1% (12/21) in G6PD deficient, G6PD normal, and heterozygous patients, and was not significantly different between the status (trend x2 = 0.105, p = 0.949)." (PMID 35279143, 2022). "Deficiency of G6PD (estimated at 24% amongst male Bahrainis and 6–13% amongst male Saudis) may also contribute to anemia in the region, owing to its impact on oxidative stress and hemolysis." (PMID 33801513, 2021). "The proportion of patients with hemoglobin decline ≥25 g/L or 25% from baseline (15.0% vs. 3.3%; p = 0.006) and anemia (30.0% vs. 14.6%; p = 0.016) after aspirin treatment was higher in the G6PD‐deficient group, which was accompanied by a more significant bilirubin increase." (PMID 34369077, 2021). "In contrast, in G6pd deficiency group, only less than 20% (heterozygote) and 40% (hemizygote and homozygote) of the mice died during this period, whereas rest of the mice died between 12 to 24 days post-infection and mostly died from anemia." (PMID 34456927, 2021). "Numerous medications have been reported to cause anemia in G6PD-deficient individuals." (PMID 32884875, 2020). "Similarly, the sample size was too low to detect any association between G6PD status in boys and anemia." (PMID 31792345, 2019). "Nevertheless, two G6PD-deficient males with HbAE displayed severe anemia with Hb levels below 80 g/L, suggesting that co-inheritance of the G6PD deficiency and HbAE may have more severe impacts on Hb levels in males." (PMID 28531196, 2017). "However, the fall in Hb concentration at day 7 was greater in G6PD-deficient patients who received primaquine than in those who did not and one patient who received primaquine developed moderately severe anemia." (PMID 28605472, 2017). "The degree of haemolysis depends on total dose of primaquine (PQ), underlying G6PD variant and age of the RBC population (with lower G6PD activities in older cells); depending on conditions, haemolysis can be slow and self-limited or result in acute and potentially fatal anaemia." (PMID 28893237, 2017). "This will allow a better comprehension of the relationship between drug dosage and haemolysis in subjects with different G6PD variants and activity levels in subjects with virtually any haematologic picture (including anaemia of various aetiologies and abnormal haemoglobins)." (PMID 28852037, 2017). "Although, in most cases, G6PD-deficient individuals appear normal, it can lead to life threatening anemia in severely G6PD-deficient individuals during oxidative stress induced by foods (fava beans, legumes), drugs (primaquine, sulfa drugs) and infection with microorganisms." (PMID 27880809, 2016).
anemia (continued). "In the population under study, anaemia caused by several factors is found in over 15% of women and expressing G6PD activity as U/RBC might be more accurate in this portion of population." (PMID 27035821, 2016). "Male hemizygotes of G6PD rs1050828 (OR = 3.01, 95%CI 1.26-7.18, p = 0.009) and females with rs1050828 (CT/TT vs. CC, OR = 2.47, 95%CI 1.34-4.56, p = 0.003) and rs1050829 (CT/TT vs. CC, OR = 1.88, 95%CI 1.20-2.93, p = 0.005) SNPs of G6PD were more susceptible to anaemia." (PMID 24934404, 2014). "All reported pediatric cases of HIHA in G6PD deficient share the same underlying pathophysiology of oxidative stress-induced hemolytic anemia, with clear laboratory evidence of hemolysis in the form of anemia, reticulocytosis, blood film evidence, and/or high LDH." (PMID 36879691, 2023). "Among different anemias, the hemolytic one is a common class of anemia that may be inherited (due to deficiency of glucose-6-phosphate dehydrogenase) or acquired (due to exposure to hemolytic agents) with the result of intra- or extra-vascular destruction of RBCs." (PMID 30328935, 2018). "When anaemia is caused by abnormal Hb variants, questions could be raised about the haemolytic risk associated with 8-aminoquinoline treatments in carriers of both Hb variants and G6PD mutations." (PMID 28852037, 2017). "Nevertheless, two G6PD-deficient males with HbAE were severely anemic with Hb levels of < 80 g/L, suggesting that co-inheritance of these two traits may have more drastic effects on anemia in males." (PMID 28531196, 2017). "There was a high (57.5%) prevalence of G6PD-induced anaemia among children attending Jos University Teaching Hospital, Nigeria." (PMID 41200155, 2025). "This study has objectively established high prevalence of anaemia, G6PDD and G6PDD-induced anaemia in children aged 0–5 years in Jos, Nigeria, highlighting the importance of G6PD screening in children." (PMID 41200155, 2025). "Pre-treatment severe anaemia (<7 g/dL) was reported for 42 (0·7%) of 5712 patients: 32 (0·8%) of 3776 were G6PD normal, four (0·3%) of 1522 were G6PD intermediate, and six (1·4%) of 414 were G6PD deficient." (PMID 38365417, 2024). "Realizing early-onset anemia in newborns and its consequences, the newborn G6PD screening program has been conducted in several maternity centers since 2010 in Vietnam." (PMID 38553482, 2024). "This reflects fluctuating levels of awareness and understanding of G6PD anemia among the surveyed participants." (PMID 38125694, 2023). "This is in agreement with the increased percentages of the pregnant women carrying G6PDd who showed anemia in comparison the with normal G6PD women." (PMID 37568487, 2023). "Increased bilirubin synthesis occurs in haemolytic conditions like glucose 6-phosphate dehydrogenase deficiency (G6PD), sickle cell disease, ABO, and rhesus incompatibility, etc., resulting in anaemia." (PMID 38111630, 2023). "The inherited disorders of the participants were noted as follows: sickle cell disease in 70 (34.5%) respondents, anemia in 54 (26.6%), 37 (18.2%) had G6PD, and 33 (16.3%) had thalassemia." (PMID 38125694, 2023). "On the contrary, a study in South Africa found a significant increase in the prevalence of anaemia during follow-up only in G6PD normal patients." (PMID 35279143, 2022). "Despite normal G6PD activity, 22% of heart transplant recipients receiving dapsone for PJP prophylaxis developed anemia with at least a probable causal association by the Naranjo Adverse Drug Reaction Probability scale." (PMID 36362606, 2022). "Dapsone-related anemia has been reported in the setting of normal G6PD activity resulting in dapsone discontinuation in 46% of kidney transplant recipients and 23% of lung transplant recipients." (PMID 36362606, 2022). "In real situations, before primaquine treatment can be re-considered for these patients, quantitative G6PD testing will be required after anaemia is corrected." (PMID 34353361, 2021).
anemia (continued). "At presentation, the geometric mean parasite count was 9463/μL (95% CI 6757–13,254), and 24 (49%) patients had anaemia (using WHO age-related criteria), 3 (6%) patients had acute kidney injury (KDIGO criteria) and a single patient was G6PD deficient." (PMID 30526613, 2018). "More patients in the CQ + PMQ group were treated for anemia than in the AS or CQ groups; 4 of 9 (44%) were G6PD-heterozygous females." (PMID 29889239, 2018). "One patient presented with moderately severe anemia (Hb < 8 g/dL), a man in the AL + primaquine group, whose baseline Hb was 12 g/dL and who was G6PD-normal." (PMID 28605472, 2017). "Around 82.6% of the G6PDd individuals have had at least one episode of anaemia, jaundice or black urine, compared to 38.5% in G6PD normal individuals." (PMID 28619120, 2017). "As a response erythropoiesis increases and lysed cells are replaced by younger cells with higher G6PD activity ultimately stabilizing and reversing anaemia." (PMID 28893237, 2017). "In the context of rare anemias, glucose-6-phosphate dehydrogenase (G6PD), hexokinase (HK), phosphofructokinase (PFK), and pyruvate kinase (PK) are enzymes that can be affected." (PMID 27471472, 2016). "It has been established by several studies that there is improvement in maternal anaemia at delivery after several doses of SP, though none of these studies compared this outcome in relation to the G6PD status of the women." (PMID 26327623, 2015). "Biochemical approaches are also affected by the duration of malaria infection, anaemia of the patient, and other haematological parameters, further increasing the chances of misclassifying a G6PDd person as G6PD normal." (PMID 25971688, 2015). "Our study demonstrates that hemodialysis adequacy plays an important role in correcting anemia in patients with ESRD on regular HD by enhancing the activity of erythrocyte G6PD activity." (PMID 25261071, 2014). "Even so, a number of marginal susceptibility genotype associations were also observed between specific gene mutations and anaemia (GBP7), CM (CD40LG), hyperparasitaemia (NOS2), hyperpyrexia (CD36, CD40LG, G6PD), SMA (EMR1) and UM (NOS2, EMR1)." (PMID 24934404, 2014). "We conducted this study to determine the G6PD activity level in patients with ESRD on maintenance HD and to study the effect of hemodialysis adequacy on G6PD activity levels and its impact on anemia." (PMID 25261071, 2014). "Our study demonstrated the beneficial effect of adequate hemodialysis in correcting anemia by enhancing the erythrocyte G6PD activity in patients." (PMID 25261071, 2014). "In our study, we suggest that hemodialysis, by removal of G6PD enzyme inhibitors, plays an important role in the improvement of anemia in patients with ESRD as suggested by previous studies." (PMID 25261071, 2014). "Additional factors, such as infections, glucose-6-phosphate dehydrogenase (G6PD) deficiency, and hemoglobinopathies, are understudied contributors to anemia in tropical settings." (PMID 22574149, 2012). "G6PD genotype was determined to assess the interaction between treatment and G6PD status in their effects on anaemia." (PMID 21666744, 2011). "Among G6PD normal children, severe anaemia was detected in 2/507 treated with AL and 12/513 treated with CD." (PMID 21666744, 2011). "In our study anaemia after treatment was more common with CD, but the low frequency of the G6PD A- genotype limited the power of our study to assess this interaction with genotype." (PMID 21666744, 2011). "Severe anaemia by day 7 was associated with lower baseline haemoglobin concentration, hyperparasitaemia, and low transmission intensity but not with age group, G6PD status, or primaquine dose." (PMID 40286803, 2025). "There was no increase in anaemia-associated declines in haemoglobin concentration (>25%) at a primaquine dose of 0·25 mg/kg, regardless of age group, transmission setting, and glucose-6-phosphate dehydrogenase status." (PMID 40286803, 2025).
anemia (continued). "Furthermore, of females with inherited anemias, the G6PD trait alone accounted for the vast majority." (PMID 38079097, 2024). "In connection with the landmark discovery that female erythrocytes are mosaic for G6PD due to inactivation of one of the X chromosomes, the high frequency of female anemia in the region suggests the need for a close examination of the functional G6PD deficiency status of pregnant women." (PMID 37568487, 2023). "Despite normal G6PD activity, anemia can still occur while on dapsone therapy." (PMID 36362606, 2022). "Possible haemolysis from oxidative states in sickle cell patients and following IPTp administration in G6PD women may further compound maternal anaemia." (PMID 36303165, 2022). "Medication, hemolysis, and anemia can affect the detection of G6PD activity." (PMID 36704359, 2022). "Anemia from dapsone may occur in a significant proportion of patients despite normal G6PD activity and resulting in significant morbidity." (PMID 36362606, 2022). "More than half of the patient population (54–57%) in the present study had varying degrees of anaemia, which may lead to an unreliable measurement of G6PD activity." (PMID 34353361, 2021). "Typically, the G6PD A(-) variant does not manifest anemia until it is exposed to an oxidant drug or challenge such as SARS-CoV-2-infection, leading to an episode of acute intravascular hemolysis." (PMID 34178542, 2021). "The distribution of anaemia in different age groups in both sexes and the distribution of G6PD enzyme activity according to sex and age groups suggested that bias may have been introduced due to the presence of many patients with different levels of anaemia." (PMID 34353361, 2021). "Variations in individual hematocrit levels and anemia are known to affect the reliability of G6PD enzyme activity measurements, and could have affected test results here, but they are not routinely measured." (PMID 34003840, 2021). "The prevalence of anemia without any intervention was already high (43.0%) in this population and even higher (49.6%) for the G6PD-deficient individuals." (PMID 34627346, 2021). "For example, one relationship is G6PD:202A – chloroquine – anemia, stating that patients with the 202A version of the G6PD gene and treated with chloroquine (an anti-malarial drug) are likely to experience anemia (an abnormally low level of red blood cells in blood)." (PMID 30999867, 2019). "A 22 months old child (G6PD normal) in the MB arm developed severe anaemia as defined in the present study (haemoglobin value dropped from 7.1 g/dl on day 0 to 5.8 g/dl on day 3), was hospitalized and received a blood transfusion, afterwards the child fully recovered." (PMID 31600221, 2019). "However, some evidence of a reassuring safety profile in the broader target population was generated by defining the prevalence of anaemia and G6PD/CYP2D6 genotypes among all those screened." (PMID 31234865, 2019). "One G6PD normal patient who received primaquine developed moderately severe anaemia (Hb < 8 g/dL)." (PMID 28605472, 2017). "Anemia alone profoundly impacted observed G6PD activity measurements." (PMID 25746733, 2015). "Extensive investigation was performed to determine the cause of anemia and hemolysis which included tests for cord blood glucose-6-phosphate dehydrogenase (G6PD) and parvovirus B19, both of which were negative." (PMID 26682081, 2015). "Most G6PD-deficient individuals in our survey were apparently healthy (with no sign of severe anemia), and genotyping analysis showed that over 80% of the females were heterozygous for the studied G6PD mutant alleles." (PMID 26226515, 2015). "Meanwhile, individuals with the EMR1 rs373533 GT, EMR1 rs461645 CT and RTN3 rs542998 (additive C) genotypes were more susceptible to hyperpyrexia while both females and males with the rs1050828 and rs1050829 SNPs of G6PD, respectively, were more vulnerable to anaemia." (PMID 24934404, 2014).